KLK7 (kallikrein related peptidase 7)
Diseases named in the same sentence as KLK7 in open-access papers (continued):
Sharing a sentence is not in itself a finding about the gene and the disease.
melanoma (8 papers, 2011 to 2025). A malignant, usually aggressive tumor composed of atypical, neoplastic melanocytes. "In addition, KLK7 was found to be associated with good prognosis and survival outcome of patients with primary melanoma." (PMID 28636767, 2017). "Next, cellular invasion was assessed using an in vitro Matrigel invasion assay to determine whether the increased migration rate induced by KLK7 in melanoma cells was associated with increased invasive properties as well." (PMID 28636767, 2017). "Aberrant expression of KLK7 has found to be related to melanoma aggressiveness by stimulating cell migration and adhesion." (PMID 34603393, 2021). "Our results demonstrate, for the first time, that aberrant KLK7 expression leads to a switch from proliferative to invasive phenotype, suggesting a potential role of KLK7 in melanoma progression." (PMID 28636767, 2017). "Our results, together with those from previous reports, indicate a correlation of KLK7 expression with melanoma metastasis and suggest that KLK7 is a potential biomarker for melanoma progression." (PMID 28636767, 2017). "In conclusion, we have shown that KLK7 is an aberrantly expressed melanoma‐produced proteinase and that KLK7 decreases cell proliferation and colony formation but induces an increase in cell motility and cell invasion." (PMID 28636767, 2017). "Nevertheless, when examined by ELISA, KLK7 was found to be the most abundantly secreted protein (up to 958 ng·L−1) into the culture media of the melanoma cells." (PMID 28636767, 2017). "Herein, we demonstrate that although mRNA of several KLKs are aberrantly expressed in melanoma cell lines, only the KLK7 protein is highly secreted in vitro." (PMID 28636767, 2017). "These experiments suggest that KLK7 activates the MAP kinase pathway in melanoma cells, possibly playing an important role in melanoma proliferation." (PMID 28636767, 2017). "KLK7 displayed ectopic expression in melanoma cells in vitro and in resected tumors from patients with primary and metastatic melanomas but was absent in nevi." (PMID 28636767, 2017). "Surprisingly, in the present study, we found that KLK7 overexpression strongly suppressed cell proliferation and colony formation of melanoma cells in vitro." (PMID 28636767, 2017). "KLK7 expression was found both in primary melanoma cell lines (such as WM115, Dauv1, HM11) and in metastatic cell lines (such as SK‐Mel 5 and MT10)." (PMID 28636767, 2017). "To validate ectopic expression of KLK7 in melanoma in vivo, we next examined the pathological relevance of our observations by performing immunohistochemistry of KLK7 in primary and metastatic melanomas versus nevi." (PMID 28636767, 2017). "Our study showed that only 69% of the analyzed melanoma cell lines ectopically express KLK7, whereas KLK14 and KLK6 are expressed by almost all of the cell lines." (PMID 28636767, 2017). "In line with our detection pattern, more recently, KLK7 expression has been found to be increased in atypical nevi and primary melanoma compared to its expression in common nevi." (PMID 28636767, 2017). "To examine the possible function of KLK7 in melanoma cells, we stably overexpressed KLK7 in the M74 melanoma cell line, using the KLK7 expression vector pRcRSV‐KLK7." (PMID 28636767, 2017). "Furthermore, KLK7 overexpression resulted in a switch from a proliferative to an invasive phenotype in melanoma cells." (PMID 38961454, 2024). "Interestingly, analysis of the intensity of KLK7 immunoreactivity revealed that metastatic melanoma tissues showed a higher average of cells with strong intensity compared to primary melanoma (13.5% versus 3.5%)." (PMID 28636767, 2017). "The melanoma tumor specimens were only investigated by immunohistochemical techniques and not by RT‐PCR because the melanoma specimens contain keratinocytes of the stratum corneum and stratum granulosum, which are a major source of KLK7." (PMID 28636767, 2017).
melanoma (continued). "The KLK7‐mediated loss of E‐cadherin and gain in MCAM/CD146 may suggest a possible role of KLK7 in melanoma cell aggregation, a known mechanism of chemoresistance in cancer." (PMID 28636767, 2017). "In addition, melanoma cells that overexpress KLK7 exhibited a significant increase in cell migration and invasion." (PMID 28636767, 2017). "Although KLK7 has been described as a biomarker in many types of cancers, to our knowledge, this is the first report demonstrating a role for KLK7 in the metastatic process of melanoma." (PMID 28636767, 2017). "Furthermore, we clearly show that KLK7 overexpression in melanoma cells induces a decrease in cell proliferation and colony formation." (PMID 28636767, 2017). "This suggests that KLK7 upregulation in melanoma may be rather influenced by other factors from the tumor microenvironment." (PMID 28636767, 2017). "Although previous studies have suggested that KLK7 acts as a proliferative factor in a number of cancer types, in the M74‐D6 and M74‐H melanoma cell lines, KLK7 overexpression surprisingly suppressed cell growth compared to M74‐mock cells." (PMID 28636767, 2017). "Interestingly, overexpression of KLK7 induced a significant reduction in melanoma cell proliferation and colony formation." (PMID 28636767, 2017). "To identify the role of KLK7 in melanoma progression, we measured the in vitro invasive potential." (PMID 28636767, 2017). "This suggests that KLK7 expression may represent a potential marker for melanoma progression." (PMID 28636767, 2017). "Thus, KLK7 may be an aberrantly expressed melanoma‐produced proteinase with tumorigenic functions and may represent a potential key element in melanoma progression." (PMID 28636767, 2017). "As demonstrated by immunohistochemistry, our analysis clearly shows that KLK7 is highly expressed in both primary melanoma and metastatic melanoma tissues, but only low KLK7 levels, if at all, are seen in nevi or in the normal melanocytes in the healthy skin, from which these cancers may arise." (PMID 28636767, 2017). "Interestingly, KLK7 was the major secreted KLK by human melanoma cell lines." (PMID 28636767, 2017). "We found that kallikrein-related peptidase 7 (KLK7) and keratin 7 (KRT7) were the most related genes in melanoma and renal cancer separately." (PMID 34603393, 2021). "Particularly, KLK7 was found to be the major secreted KLK in melanoma in vitro and was ectopically expressed in vivo in resected human melanoma tissues as well." (PMID 28636767, 2017). "Previous studies showed that KLK7 also cleaved pro‐MMP9 generating active MMP9, and uPAR, two members of key proteolytic systems in melanoma invasion." (PMID 28636767, 2017). "Thus, we hypothesize that KLK7 may represent a potential biomarker for melanoma progression." (PMID 28636767, 2017). "Some of these genes had already been described in earlier studies as being down-regulated during melanoma progression: COL17A1, DSC3, KLK7, SLPI and KLK8, or over-expressed, e.g. CCL20, THBS1 and THBS4." (PMID 22032772, 2011). "Our findings showed that the well studied KLK7 and other hKLK members (KLK6, 8 and 13) were coordinately expressed during melanoma progression: These findings were also validated in an independent dataset." (PMID 22032772, 2011). "The present study confirms these associations at the transcriptional level and shows that not only KLK6 and KLK7 but other hKLKs such as KLK8 and KLK13 are probably coordinately involved in melanoma progression." (PMID 22032772, 2011). "(2013) found that KLK7 was downregulated in ulcerated primary melanoma compared with nonulcerated tissues." (PMID 28636767, 2017). "This study was the first to report a coordinated decrease in mRNA expression levels of hKLKs (KLK6, KLK7, KLK8 and KLK13) as melanoma cells emerges from primary to metastatic phenotype, suggesting a role of these proteases in the epithelial-mesenchymal transition of primary melanoma cells." (PMID 22032772, 2011).
melanoma (continued). "KLK7 was not or barely detected in nevi, but clearly elevated in primary and metastatic melanomas." (PMID 28636767, 2017). "Compared to melanomas without ulceration, ulcerated melanomas were characterised by downregulation of members of the kallikrein serine protease family (i.e., KLK7, KLK5, KLK11), which are related to angiogenesis and the degradation of extracellular matrix components." (PMID 23383013, 2013). "The mechanism by which KLK7 inhibits cell proliferation is not clear but may be due to cell cycle arrest or processing of repressive factors (cytokines) such as IL‐1beta, a known substrate of KLK7 (Nylander‐Lundqvist and Egelrud, 1997) that has been shown to inhibit melanoma growth." (PMID 28636767, 2017). "For melanoma progression category (T3, T4 and MM), only genes ontologically-related to hKLKs (EVPL, KLK6, KLK7, KLK8, KLK13 and SERPINB13) showed a positive and high correlation coefficient (mean of 0.971) in T4 thick melanomas (depth > 4.0 mm), but not in metastatic tumors (MM)." (PMID 22032772, 2011).
pancreatic cancer (8 papers, 2008 to 2024). "Overexpression of KLK7 in pancreatic cancer was associated with urokinase-type plasminogen activator receptor (uPAR), which inhibited cellular adherence to vitronectin." (PMID 36905477, 2023). "For example, small molecules inhibiting KLK7 have efficiently inhibited the proliferation, migration and invasion of pancreatic cancer cells, and cell shedding of plantar stratum corneum cells." (PMID 38961454, 2024). "Trichostatin A (TSA) enhanced KLK7 expression in cervical and pancreatic cancer cell lines, and the transcription factor specificity protein 1 (SP1) supported the effect of TSA on KLK7 by transcriptional activation." (PMID 36905477, 2023). "The overexpression of KLK7 can increase the proliferation abilities and promote migration and invasive behavior in pancreatic cancer cells." (PMID 33336051, 2020). "Our study suggests that KLK7 can be considerate as a novel target for anti-pancreatic cancer drug design." (PMID 29560118, 2018). "The high expression level of KLK7 in pancreatic cancer tissues is considered to be a marker for the poor prognosis of this disease." (PMID 29560118, 2018). "To study the role of KLK7 in pancreatic cancer, we established KLK7 silenced PANC-1 cells by four specific shRNAs (verified by BLAST) using lentivirus." (PMID 29560118, 2018). "Our results confirmed that KLK7 is significantly up-regulated in pancreatic cancer tissue, and knocking down or inhibiting KLK7 efficiently inhibited the proliferation, migration and invasion of pancreatic cancer cells." (PMID 29560118, 2018). "The results showed that over-expressed KLK7 promoted the proliferation, migration and invasion of pancreatic cancer cells." (PMID 29560118, 2018). "During pancreatic cancer progression, KLK7 is produced by cancer cells and released into the microenvironment." (PMID 29560118, 2018). "Short hairpin RNAs (shRNAs) were designed and constructed in lentivirus to knock down KLK7 in pancreatic cancer cell line PANC-1, and the real time cellular analysis (RTCA) was used to evaluate cell proliferation, migration and invasion abilities." (PMID 29560118, 2018). "A comparison of KLK7-transfected and vector-transfected pancreatic cancer cells reveals that hK7 expression alters cell morphology, with cells expressing hK7 exhibiting a more flattened, less refractive appearance and reduced cell-cell contacts." (PMID 19091121, 2008). "In a previous study, we have reported that kallikrein 7 (KLK7/hK7) is overexpressed in pancreatic adenocarcinomas and enhances pancreatic cancer cell invasion by shedding E-cadherin." (PMID 19091121, 2008). "In a previous report we have demonstrated that the chymotryptic-like serine protease kallikrein 7 (KLK7/hK7) is overexpressed in pancreatic cancer." (PMID 19091121, 2008). "Since BxPC-3 cells do not express hK7, we used these cells to mimic the aberrant expression of KLK7 observed in pancreatic tumors by expressing high levels of hK7 through stable transfection." (PMID 19091121, 2008). "This study suggested that KLK7 could be a potential chemotherapy target for treatment of pancreatic cancer, which would provide us a novel strategy for the treatment of this disease." (PMID 29560118, 2018). "In this work, we investigated the potential of KLK7 as a therapeutic target of pancreatic cancer." (PMID 29560118, 2018). "As a result, KLK7 reduces the aggregation of pancreatic cancer cells and enhance their migration." (PMID 29560118, 2018). "Altogether, our results suggest that KLK7 could be a chemotherapy target for the treatment of pancreatic cancer." (PMID 29560118, 2018). "Taking together, these results suggested that KLK7 could be a target to inhibit pancreatic cancer development." (PMID 29560118, 2018). "In this work, we set out to investigate whether KLK7 could be a target for the treatment of pancreatic cancer." (PMID 29560118, 2018). "Our results suggest that KLK7 could be a potential chemotherapy target for pancreatic cancer." (PMID 29560118, 2018).
pancreatic cancer (continued). "KLK6, KLK7, KLK8, KLK10 and KLK11 were coexpressed and upregulated in tissues from pancreatic cancer patients compared to normal pancreas." (PMID 34439122, 2021). "In pancreatic cancer, high KLK-7 expression is correlated with a poor prognosis, and silencing KLK-7 or the suppression of its activity with a small molecule inhibitor resulted in suppression of the proliferation, migration, and invasion of PANC-1 cells." (PMID 32948029, 2020). "Over expression of KLK7 or exogenous addition of KLK7 contributes to tumor cell migration and facilitates tumor cell invasion through releasing individual cells by cleaving junction proteins or ECM to allow movement of the pancreatic cancer cells." (PMID 29560118, 2018). "However, the effects of hK7 expression on desmosomal proteins in any type of cancer, including pancreatic cancer where overexpression of KLK7/hK7 has been clearly established, have not been studied." (PMID 19091121, 2008). "However, whether KLK7 has the potential to be a therapeutic target for the treatment of pancreatic cancer has not been studied very well." (PMID 29560118, 2018).
papillary thyroid cancer (8 papers, 2017 to 2025). "In papillary thyroid cancer, KLK7 upregulation was found to be correlated with BRAF mutations." (PMID 28636767, 2017). "Earlier studies have indicated that KLK7, KLK10, and KLK11 are linked to the survival rates and immune reactions of individuals with papillary thyroid cancer (PTC)." (PMID 39991575, 2025). "FOXD2-AS1 increases KLK7 level by interacting with miR-485-5p, thereby exacerbating cell proliferation and migration in papillary thyroid cancer." (PMID 38807101, 2024). "lncRNA NEAT1 acts as an oncogene in papillary thyroid cancer by regulating the miR‐129‐5p/KLK7 axis." (PMID 35242185, 2022). "For instance, lncRNA FOXD2-AS1 controlled the miR-485-5p/KLK7 axis to enhance papillary thyroid cancer progression, which revealed that FOXD2-AS1 acted as a ceRNA to increase the expression of KLK7 through sponging miR-485-5p in papillary thyroid cancer." (PMID 31462944, 2019). "Additionally, FOXD2-AS1 functioned as a molecular sponge of miR-485-5p to control KLK7 transcription, displaying that the FOXD2-AS1/miR-485-5p/KLK7 axis controlled the progression of Papillary thyroid cancer (PTC)." (PMID 38485838, 2024).
colorectal cancer (7 papers, 2016 to 2025). A primary or metastatic malignant neoplasm that affects the colon or rectum. "The expression level of KLK7 is correlated with prognosis of liver metastasis in patients with colorectal cancer." (PMID 28678795, 2017). "Furthermore, it establishes role of TRIP13 in colorectal cancer metastasis and identifies COL6A3, TREM2, SHC3, and KLK7 as its downstream targets." (PMID 33037736, 2020).
cervical cancer (5 papers, 2013 to 2025). A primary or metastatic malignant neoplasm involving the cervix. "Herein, we demonstrated an aberrant expression of matriptase, KLK5, and KLK7 in human biopsies from patients with early cervical cancer (high-grade intraepithelial lesion - HSIL)." (PMID 40753921, 2025). "Since KLK7 is overexpressed in human pancreatic ductal adenocarcinomas and cervical cancer cells (Raju, Kaushal, & Haun, 2016), it appears to be an interesting target for specific protease inhibitors." (PMID 29210603, 2018). "This study underscores the critical roles of serine proteases KLK5, KLK7, and KLK14 in cervical carcinogenesis, suggesting that these serine proteases are promising targets for the development of novel therapeutic strategies in cervical cancer." (PMID 40753921, 2025). "•Serine proteases KLK5, KLK7, and KLK14 are upregulated in HPV-driven cervical cancer." (PMID 40753921, 2025).
colon adenocarcinoma (5 papers, 2018 to 2025). "KLK6, KLK7, KLK8, and KLK10 were recently reported as potential diagnostic biomarkers for colon adenocarcinoma." (PMID 36293321, 2022). "Recent analysis of kallikrein gene family across 15 different cancers highlighted KLK6, KLK7, KLK8, and KLK10 as the excellent diagnostic biomarkers candidates for colon adenocarcinoma." (PMID 34065672, 2021). "KLK6, KLK7, KLK8 and KLK10 are considered as excellent biomarker candidates in diagnosing colon adenocarcinoma." (PMID 40156045, 2025).
dermatitis (5 papers, 2016 to 2023). An inflammatory process affecting the skin. "Thus, KLK7 has been linked to several skin disorders including dermatitis, psoriasis and the Netherton syndrome." (PMID 29210603, 2018). "In addition, the expression level of filaggrin was reduced by C3A and GGRT treatment, and the expression levels of dermatitis-related proteins, including KLK7, PAR-2, TSLP, and IL-4, were markedly recovered." (PMID 34946332, 2021). "The protective effects of PF and PW on UVB-induced skin inflammation and skin barrier damage in human immortalised epidermal keratinocytes (HaCaT) cells (including cell viability, ROS, HO-1, NQO1, IL-1β, IL-8, TNF-α, KLK-7, FLG, AQP3 and Caspase 14 levels) are investigated." (PMID 36771204, 2023).
inflammatory skin disease (5 papers, 2018 to 2025). Inflammatory skin disorders covers a broad category that includes many conditions ranging in severity, from mild itching to grave medical health complications These disorders are common in people of all ages and races. "Previously, other KLKs, i.e., KLK5 and KLK7 had been validated as drug targets in skin inflammatory diseases in which the implication of KLK proteolytic cascades is well-defined in vivo." (PMID 35652924, 2022). "Studies on KLK7 function in vivo have focused on inflammatory skin diseases and with the finding of amyloid β-peptide cleavage also Alzheimer’s disease." (PMID 28932870, 2018).
ovarian tumor (5 papers, 2008 to 2020). "KLK6 and KLK7 mRNA and protein overexpression is directly associated with early-stage ovarian tumors and can be measured in patient tissue and serum samples." (PMID 25477184, 2014). "Within our recent project, we observed robust mRNA expression patterns of KLK5 and KLK7 (this study) in the majority of ovarian tumor tissues, which were in line with data from The Cancer Genome Atlas (TCGA)." (PMID 33087135, 2020). "Furthermore, KLK7 expression has been found up-regulated in breast and ovary tumors and is being considered a new tumor progression marker." (PMID 18588690, 2008).